LAG3 (lymphocyte activating 3)
Diseases named in the same sentence as LAG3 in open-access papers (continued):
Sharing a sentence is not in itself a finding about the gene and the disease.
tumor (continued). "LAG-3 is expressed on tumor-infiltrating T cells with defective cytokine production and on Tregs." (PMID 35874717, 2022). "Moreover, strong negative correlations were observed between levels of FoxP3−Helios− T cells with CD4+TIM-3+ T cells and CD4+LAG-3+ T cells in tumor tissues (r = −0.825, p < 0.0001; r = −0.672, p = 0.0006, respectively) but not in PBMCs and NILs." (PMID 35455287, 2022). "Additionally, CD8+ T cells in the tumor of the AR group showed increased expression of exhausted genes (PD‐1, LAG‐3)." (PMID 35224894, 2022). "LAG-3 expression levels correlate with tumor progression and poor prognosis." (PMID 35874717, 2022). "Also, when comparing the tumors with the matching healthy renal tissues, we noticed that immune checkpoint receptors (LAG-3 and PD-1) were highly expressed in the tumor compared to the healthy kidney." (PMID 35003893, 2022). "To verify whether the novel tribodies targeting PD-L1, PD-1 and LAG-3, efficiently induce the activation of lymphocytes against cancer cells, we investigated their effects on co-cultures of tumor cells and lymphocytes." (PMID 36071464, 2022). "In transplanted tumor mice, the anti-LAG-3 antibody combined with the anti-PD-1 antibody could treat the vast majority of mice, prolonging their survival period and improving tumor removal ability." (PMID 35892835, 2022). "The phenomenon is most obvious in CD8+ TILs in which LAG-3 is highly expressed and combined with its ligand and is detected on the cancer cell surface, leading to the decline or exhaustion of T-cell function and thereby promoting tumour immune escape." (PMID 35494015, 2022). "Taken together, LAG-3 inhibitors may have a better therapeutic effect, further demonstrating a novel tumor immunotherapy target of LAG-3 beyond PD-1/PD-L1 and CTLA-4." (PMID 35958563, 2022). "Blockage of LAG-3 signaling could be used to activate anti-tumor immunity; however, inhibition of the LAG-3 pathway alone has been ineffective." (PMID 36135216, 2022). "We next explored whether LAG3 levels had prognostic value and whether this depended on the tissue site queried (i.e., primary tumor versus metastases)." (PMID 36313654, 2022). "PD-L1/LAG-3 bispecific antibody induced stronger anti-tumor effect than each parental antibody." (PMID 35874717, 2022). "Antagonizing LAG-3 can restore the anti-tumor activity of T cells." (PMID 36225938, 2022). "Interestingly, we found that the addition of the anti-PD-L1, -PD-1 or LAG-3 mAb to the tribody significantly increased the tumor cells lysis accordingly to the higher secretion of IFNγ cytokine, detected after treatments." (PMID 36071464, 2022). "However, αTIGIT + bintrafusp alfa Responders had the highest frequency of dual-positive CD8+ T cells co-expressing PD-1 and LAG3 per mg of tumor in comparison to all other treatment groups (p < .0001)." (PMID 36211806, 2022). "As has been reported previously, treatment with anti-PD-1 agents may induce the expression of other checkpoint molecules, such as TIM-3 and LAG3, and dual-blockade of PD-1/TIM-3 or PD-1/LAG3 has been shown to enhance the anti-tumour response." (PMID 35017553, 2022). "In addition to LAG-3 expression, tumor grading (HR 2.583; 95% CI 1.591–4.192; p < 0.001) and tumor size (HR 1.626; 95% CI 1.020–2.591; p = 0.041) were also identified as independent prognostic factors in the multivariate Cox regression analysis." (PMID 36289918, 2022). "LAG-3 can negatively regulate the function of T cells, exerting important effects on maintaining the homeostasis of the immune system under normal physiological conditions and promoting tumor cells immune escape in the tumor microenvironment." (PMID 35958563, 2022). "Interestingly and likely in line with our results, LAG3 expression levels on tumour infiltrating lymphocytes (TILs) of LC patients has been shown to correlate with early disease relapse and poor prognosis." (PMID 35625783, 2022).
tumor (continued). "Perhaps indicative of the modest effect of LAG-3 blockade as a monotherapy in human cancers and mouse tumour models complete knockout of LAG-3 in mice displayed normal immune function – in stark contrast to the lymphoproliferative disease observed in CTLA-4 knockout mice." (PMID 35265944, 2022). "Surgically resected UPS samples were stained by immunohistochemistry (IHC) for the following: tumor-associated immune cells (CD3, CD8, CD163, CD20), immune checkpoints (stimulatory: OX40, ICOS; inhibitory: PD-L1, LAG3, IDO1, PD1), and the adenosine pathway (CD73, CD39)." (PMID 36313661, 2022). "LAG-3 inhibits the anti-tumor effect of anti-PD-1 and anti-LAG3 therapy in HL by inhibiting the CD4+ T cell responses; chemotherapy with ABVD (doxorubicin, bleomycin, vinblastine, and dacarbazine) shows little therapeutic effect with a higher infiltration of LAG-3+TILs." (PMID 36077354, 2022). "It has also been suggested that positive expression of LAG-3 in tumor cells may be a predictor of improved relapse-free survival in endometrial cancer." (PMID 36359346, 2022). "LAG-3 was also found to be co-expressed with PD-1 in the tumor microenvironment." (PMID 35958563, 2022). "Still, our findings demonstrate that the type of tumor tissue being evaluated may have large effects on the prognostic and predictive power of certain biomarkers, including LAG3." (PMID 36313654, 2022). "MHC II− tumor cells, suggesting that LAG-3–expressing TILs may be preferentially located in proximity to MHC II+ tumor cells, allowing for LAG-3 activation and the inhibition of antitumor immunity." (PMID 34611303, 2022). "In contrast to cold tumours, hot tumours are characterised by considerable immune cell infiltration, particularly that of cytotoxic T cells, in addition to high expression of immune checkpoint molecules, such as PD-1, PD-L1, and LAG3." (PMID 35610596, 2022). "Interestingly, we found that there is a strong correlation between the RNA expression of EOMES and that of LAG3 in CD8+ cells in those tumor samples showing higher percentage of mature DCs, immature DC, PD-L1+ M1 macrophages or PD-L1+ M2 macrophages." (PMID 35346322, 2022). "Definition of LAG-3 expression and purpose on tumour cells might reveal a novel insight about LAG-3 function." (PMID 35265944, 2022). "However, when mice were treated with a small-molecule inhibitor of the PI3Kδ subunit which reduced Treg function and allowed an immune response to develop in some mice, LAG-3 blockade displayed a strongly potentiating effect on anti-tumour immunity." (PMID 35265944, 2022). "Moreover, some studies have shown that PD-1 and LAG-3 are co-expressed in the tumor immune microenvironment, which jointly mediates the immune escape effect of tumor cells." (PMID 36518768, 2022). "LAG-3 has become a novel tumor immunotherapy target beyond CTLA-4 and PD-1/PD-L1." (PMID 35958563, 2022). "Considering the robust LAG3 expression in the tumor microenvironment and its correlation with poor prognosis in MM and other cancers, targeting the LAG3-specific inhibitory pathway may enhance anti-MM immunity and have a more favorable therapeutic index." (PMID 34290359, 2022). "As LAG-3 is involved in the pathogenesis of a wide range of non-neoplastic disease, it could be a therapeutic target for the treatment of selected pathologies." (PMID 35755891, 2022). "The LAG-3 expression may play a role as a predictive marker; in LAG-3 positive patients the response was significantly higher than in patients with a LAG-3 presence of less than 1% of positive tumor cells, the response rate equaled 20% vs. 7%." (PMID 36077354, 2022). "LAG3 is also a predictor of tumor response following therapy for HCC." (PMID 35734429, 2022). "It is possible that these broadly targeted effects on the tumor transcriptional state could increase sensitivity to more broadly used immunotherapies, such as the anti-LAG3 antibody." (PMID 36139469, 2022).
tumor (continued). "With these immunosuppressive environments, inhibitory receptors including programmed cell death protein 1 (PD-1), cytotoxic T lymphocyte-associated protein 4 (CTLA-4), and lymphocyte activation gene (LAG-3) are upregulated in tumor cells and APCs to further inhibit the T cell effector functions." (PMID 35806328, 2022). "Moreover, enhanced expression of LAG3 on CD8 T cells reveals their dysfunction in anti-tumour activity, thus being an important target for blocking checkpoint in cancer immunotherapy." (PMID 36299526, 2022). "Taken together, drebrin+ T cells co-expressed multiple exhaustion-associated molecules, including PD-1, TIM-3, LAG-3, and CXCL13, and drebrin was selectively expressed in exhausted tumor-infiltrating CD8+ T cells, suggesting that drebrin is a novel exhaustion-associated molecule." (PMID 36430217, 2022). "However, the synergistic effects based on anti-PD-1 and anti-LAG-3 need to be further confirmed in different tumours through more clinical trial data." (PMID 35494015, 2022). "Moreover, ICI treatment response can be predicted by measuring the co-expression of inhibitory receptors, such as LAG3 and PD-1, both cell exhaustion markers, on tumor infiltrating lymphocytes (TILs)." (PMID 35625811, 2022). "In tumoral diseases and chronic infections, LAG-3 seems to plays a synergistic role with PD-1 to hinder immune response, therefore its inhibition could be useful as a therapeutic option." (PMID 35743435, 2022). "This is an important sign of the anti-tumor effect of bispecific antibody against PD-1/LAG-3." (PMID 36518768, 2022). "Additionally, tumor growth is further inhibited when anti-LAG3 antibodies and GSK-3 inhibitors are used in combination in mice." (PMID 35911672, 2022). "Interestingly, we found higher expression of Ctla4 and Lag3 in Myc-R26Met compared with Alb-R26Met tumours." (PMID 36433941, 2022). "In addition, LAG-3 was also observed to be upregulated in CD8+ T cells stimulated with tumor antigens." (PMID 35958563, 2022). "Moreover, confocal fluorescence imaging of HCC tumour and peri‐tumour tissues indicated that all γδ T cells (Vδ1+ and Vδ2+) sturdily express LAG3, whereas PD1 was almost undetectable." (PMID 35390227, 2022). "We found that MWA could greatly induce the expression of LAG3 on tumor-infiltrating lymphocytes (TILs) in MC38 tumors." (PMID 36180876, 2022). "In contrast, in a multivariate Cox regression analysis, adjusted for age, tumor size, axillary nodal status, histological grade of differentiation and proliferation marker Ki-67, LAG-3 showed a significant influence on MFS (HR 0.574; 95% CI 0.369–0.894; p = 0.014)." (PMID 36289918, 2022). "At primary tumor locations, there was no clear association between LAG3 in the primary tumor and OS after nephrectomy." (PMID 36313654, 2022). "However, anti-PD-L1 treatment resulted in upregulation or downregulation of numerous genes in CD45+ tumor-infiltrating immune cells in TCh3 tumors, including Cd3d, Cd3e, Cd3g, Cd8a, Cd8b1, Nkg7, Ccl5, Ets1, Icos, Cxcr6, Pdcd1, Lag3, Prf1, and Gzmb (right)." (PMID 35366939, 2022). "Anti-LAG-3 antibodies slow tumor growth in mouse model of fibrosarcoma." (PMID 35874717, 2022). "This approval is especially notable since it validates a completely novel combination of two immunotherapies that may work in tandem to enhance anti-tumor response by targeting LAG-3 and PD-1, two separate immune checkpoints." (PMID 36551910, 2022). "Tumor tissues enriched with cholesterol in tumor-infiltrating CD8+T cells are positively and progressively associated with upregulated expressions of PD-1, 2B4, TIM-3, and LAG-3." (PMID 36003368, 2022). "Interactions between LAG-3 and its ligands impair anti-tumor immunity." (PMID 34885076, 2021). "One possible explanation is that the presence of LAG-3 expressing TILs may indicate an ongoing cancer-immune interaction, a phenotype defined as an inflamed tumor, which usually signifies somewhat improved prognosis." (PMID 34267742, 2021).
tumor (continued). "Tumor-infiltrating NK cells expressed high levels of TIGIT, and TIGIT+ NK cells displayed impaired activity associated with increased expression of the inhibitory receptors TIM-3 and LAG-3 in comparison with TIGIT− NK cells." (PMID 34885076, 2021). "We subsequently evaluated if post-TACE serum LAG-3 level might also has a value for predicting tumor response to TACE." (PMID 34691076, 2021). "Upon engagement with MHC class II molecules, or its newly described ligand, fibrinogen-like protein 1 (FGL1), LAG-3 negatively regulates T and NK cells, thereby promoting tumor escape likely by promoting exhaustion in combination with other checkpoints such as PD1." (PMID 33925565, 2021). "Interestingly, single target blockade of LAG3 had a limited effect on both resolution of chronic infection and tumor clearance in mouse models with exhausted T cells." (PMID 33919570, 2021). "Besides PD-1 and CTLA-4, other immune checkpoints (e.g., LAG-3 and Tim-3) are involved in the immune escape of tumor cells and resistance to ICIs." (PMID 33746989, 2021). "The percentage of LAG-3+ cells was significantly elevated in tumor-infiltrating CD8+ T cells (80.27 ± 6.89%) when compared with peripheral CD8+ T cells either from NC (64.67 ± 7.43%, LSD-t test, P = 0.0001) or from GC patients (66.18 ± 8.57%, LSD-t test, P = 0.0004)." (PMID 34620075, 2021). "LAG-3 synergizes with PD-1, often co-expressed in TILs, to inhibit T cells in murine tumour models." (PMID 34968365, 2021). "In a mouse tumor model, TI PD-1+ cytotoxic Tconvs also express LAG3." (PMID 34901012, 2021). "Immunochemistry of tumor tissues of patients suggest that the expression levels of PD-1, PD-L1, CTLA-4, TIM-3, and LAG-3 are significantly higher in BRAF mutated samples than in BRAF wild-type samples." (PMID 34381786, 2021). "The results showed that the expression level of programmed death 1 (PD-1), PD-L1, indoleamine 2,3-dioxygenase 1 (IDO), and lymphocyte-activating 3 (LAG3) in METCorC1 was higher than in METCorC2 (p < 0.05), suggesting the deep contribution of tumor immune evasion in METCorC1." (PMID 34539658, 2021). "In silico analysis showed that lenalidomide, but not rituximab or fludarabine-chlorambucil regimen, significantly increased LAG-3 expression on leukemic cells, suggesting that LAG-3 blockade may potentiate the anti-tumor effect of the immunomodulatory drug." (PMID 33925565, 2021). "However, since this is the first study to report the expression of LAG‐3 and PD‐1 in tumour cells, these results require further validation." (PMID 33338327, 2021). "Moreover, at the end of IMP321 (a LAG3 antagonist) treatment, there is a 50% objective tumor response and decreased tumor size related to an increase in the absolute number of monocytic cells." (PMID 34267742, 2021). "Semblance of LAG-3+ TILs may be a predictor of existing cancer–immune interaction and present an inflamed tumor, which indicates a better prognosis." (PMID 33717059, 2021). "PD-1–treated mice had more CD8+ T cells in their tumor and more LAG-3+ TILs." (PMID 33712537, 2021). "In agreement with our flow cytometry results, we identified a significant upregulation in several genes encoding for immune checkpoint inhibitory molecules (e.g. Pdcd1, Lag3, Ctla4, Icos, Tigit, Tnfrsf18) in tumor-infiltrating CD4/ALK4-KO CD4+ T cells, compared to WT CD4+ T cells." (PMID 34548096, 2021). "Furthermore, co-expression between PDCD-1 and LAG-3 in environments containing either tumor, self-Ag, or chronic infection can result in T cells with poor effector function." (PMID 34544358, 2021). "Notably, elevated expression of LAG-3 by tumor-infiltrating lymphocytes in PDAC patients was previously detected along with increased PD-1 and CTLA-4 expression." (PMID 33803936, 2021). "In addition to LAG-3, TIM-3 is another immune checkpoint implicated in reducing the immune response in chronic inflammation and tumor infiltrating leukocytes." (PMID 33670942, 2021).
tumor (continued). "Moreover, LAG3 levels are higher in cancer cells derived from metastatic nodes and recurrent disease compared to those from the initial tumor." (PMID 34357118, 2021). "Our study highlights the biological importance of LAG-3 expression by tumor-infiltrating T cells." (PMID 33803936, 2021). "LAG-3 is a protein expressed on tumor-infiltrating lymphocytes (TILs)." (PMID 33925941, 2021). "The response to ICIs is influenced by several factors, which can be monitored using various biomarkers, including degree of CD8 + T cell infiltration, tumor mutation burden, mismatch repair, and the expression of critical immune checkpoints (PD-1, PD-L1, CTLA-4, LAG-3, TIM3, and TIGIT)." (PMID 34367952, 2021). "We reported that mouse LAG-3 (moLAG-3)-specific sdAbs can be used to quantitatively and noninvasively image moLAG-3 expression on tumor-infiltrating lymphocytes at baseline and and after induction by PD-1-blocking therapy, showing predictive value for subsequent LAG-3 blocking therapy." (PMID 34727262, 2021). "Some important immune-associated genes, such as granzyme B, IFN-γ, IL-2, IL-12, FoxP3 and STING, are regulated via epigenetic mechanisms in immune or/and cancer cells, as are immune checkpoint molecules (PD-1, CTLA-4, TIM-3, LAG-3, TIGIT) expressed by immune cells and tumor-associated stromal cells." (PMID 34930302, 2021). "Lag-3 is also co-expressed with PD-1 in tumor-infiltrating lymphocytes in tumors and synergizing with PD-1 blockade may improve tumor control or regression." (PMID 34109209, 2021). "Notably, the anti-LAG-3 Ab and anti-PD-1 Ab combination treatment more effectively delayed tumor growth than the single treatments (LBL-007 only or anti-PD-1 Ab only)." (PMID 34575943, 2021). "In addition, the results of flow cytometry analysis showed that FHVH3/VH1 CAR-T cells in the peripheral blood of tumor-bearing mice collected on day 24 exhibited lower levels of LAG-3 and TIM-3 than H65 CAR-T cells." (PMID 34274536, 2021). "There is also an almost uniform expression of the exhaustion marker TIGIT among the tumor-infiltrating Treg, while other immune checkpoint receptors associated with exhaustion (PD-1 and LAG3) were not expressed to any larger extent in the enriched clusters." (PMID 34407765, 2021). "Indeed, several early clinical trials of anti-LAG-3 monoclonal antibodies or anti-Tim-3 monoclonal antibodies combined with PD-1 inhibitors are being conducted in several tumor types, including RCC." (PMID 33746989, 2021). "Moreover, LAG-3 can bind with the LSECtin, a member of the C-type lectin receptor superfamily, typically exposed on tumor cell membranes, and with the fibrinogen like protein 1 (FGL-1), which is part of the fibrinogen protein superfamily." (PMID 34357118, 2021). "Both pre-TACE and post-TACE serum LAG-3 levels could serve as powerful predictors for tumor response of TACE, and high pre-TACE serum LAG-3 level was an indicator for poor prognosis in HCC." (PMID 34691076, 2021). "The fibrinogen-like protein 1/LAG3 combination could induce LAG3-dependent T cell suppression and result in tumor immune evasion." (PMID 34134781, 2021). "High levels of LAG3 have been found in tumor-infiltrating lymphocytes (TILs)." (PMID 34771459, 2021). "Nuclear GAL3 may promote antitumour activities while cytoplasmic GAL3 may enhance tumour aggressiveness, and this may explain the contradictory level of LAG-3 expression status in the two studies." (PMID 33921181, 2021). "In human tumor tissue, LAG-3 is co-expressed with PD-1 on activated but exhausted CD8+ T cells." (PMID 33413541, 2021). "In conclusion, our platform for discriminating the tumour profiles of three IRs, LAG-3, TIM-3, and TIGIT, may have an impact on predicting both outcome and the immune microenvironment in RCC." (PMID 34545095, 2021). "In humans, LAG-3 is expressed on CD8+ tumor-infiltrating lymphocytes (TILs) and peripheral Tregs." (PMID 34025438, 2021).